STAT3 (signal transducer and activator of transcription 3)
Diseases named in the same sentence as STAT3 in open-access papers (continued):
Sharing a sentence is not in itself a finding about the gene and the disease.
COVID-19 (continued). "The escalating activation of the STAT3-PAI-1 interactome in multiple cellular compartments drives a catastrophic cascade of life-threatening systemic events of inflammation, fibrosis, and coagulopathy/thrombosis characteristics seen in severe cases of COVID-19." (PMID 35056076, 2021). "However, whether the IL-33/MAPK/STAT3/IL-13 axis plays a positive or negative role in the pathology of COVID-19 requires further exploration." (PMID 36362440, 2022). "Interestingly, OSM also binds to the OSM receptor, leading to the recruitment of JAKs and subsequent signal transduction and activation of STAT3; thus, we can hypothesize that both CXCL9 and OSM participate in the upregulation of PD-L1 through the STAT activation pathway in COVID-19 patients." (PMID 36428847, 2022). "As STAT3 is a latent cytoplasmic transcription factor that can couple with multiple cytokines as an ultimate effector of the JAK/STAT pathway, an important question that remains unexplored is whether STAT3 might be a better target than its upstream JAK activators to clinically manage COVID-19." (PMID 32517353, 2020). "Microthrombi-positive versus microthrombi-negative COVID-19 comparisons yielded 4 tier 1 targets: PIP5K1A, STAT3, and VEGFA in fibroblasts and CSNK1A1 in pericytes." (PMID 34905515, 2022). "Type I IFN response was impaired in severe and critical COVID-19 patients: striking downregulation of ISGs, IRF-1 and STAT3, absence of circulating IFN-β in patients with all disease-severity grades and low IFN-α production in severe COVID-19 patients were reported [TE90]." (PMID 34876157, 2021).
breast tumor (142 papers, 2005 to 2026). "Previous reports have highlighted that STAT3 in breast tumor-associated CD8+ effector T cells promote FAO activity by upregulating CPT1B." (PMID 40612678, 2025). "Constitutive persistent activation of STAT3 has been implicated in the pathogenesis of whole spectrum of malignancies including that of breast tumors." (PMID 33604794, 2021). "Constitutive STAT3 activation is found in about 50–60% of the breast tumors and associated with tumorigenesis and drug resistance." (PMID 24297508, 2014). "In cell lines from brain, skin, and breast tumors, the overexpression of anti-apoptotic genes, such as Bcl-2 and Bcl-XL, is associated with constitutive STAT3 activity, and STAT3 inhibition induces apoptosis." (PMID 22177381, 2011). "Similarly, STAT3 has been implicated in herceptin-induced resistance in HER2-overexpressing breast tumors." (PMID 34697301, 2021). "It has been suggested that STAT5 activation can attenuate STAT3-driven breast tumors, offering an interesting avenue to potentially target STAT3 and use STAT5 as a prognostic marker." (PMID 40507264, 2025). "Analysis of human breast tumors showed that the IL-6/JAK/STAT3 pathway is enriched in ER + ILC compared to ER + NST." (PMID 40597443, 2025). "The upregulated IL-6 expression promotes EMT through the JAK/STAT3 signaling pathway, thereby suppresses E-Cadherin expression, and facilitates breast tumor cell migration and invasion." (PMID 40821783, 2025). "This is particularly interesting since STAT5-driven breast tumors are molecularly distinct from STAT3-driven breast tumors." (PMID 40507264, 2025). "On the contrary, lower phospho-STAT3 has been correlated with HER2-expressing tumors, suggesting that further analysis is needed to elucidate the role that STAT3 plays in HER2-positive breast tumors." (PMID 40507264, 2025). "AKT phosphorylates and inhibits salt-induced kinase 1 (SIK1), thereby relieving its inhibition on STAT3 and promoting the occurrence of breast tumors." (PMID 39859168, 2025). "Genetic ablation of STAT3 in T cells or CPT1A inhibitor treatment in obese tumor-bearing mice suppresses breast tumor progression by reducing FAO, increasing glycolysis, and enhancing CD8+ T-cell functions." (PMID 39402302, 2024). "STAT3 signaling possesses multifaceted functions in the immune response in the breast tumor microenvironment and has downstream target genes that overlap with the Wnt signaling pathway." (PMID 37185433, 2023). "In breast tumors, MDSCs exert their potent immunosuppressive functions through several pathways: (a) STAT3-NF-Κb-IDO, which is activated by tumor-derived IL-6 to activate STAT3 in MDSCs." (PMID 36982282, 2023). "Co-overexpression of these proteins was also present in lymph node metastases, and patients with co-activated STAT3/GLI1 breast tumors had poor long-term survival outcomes." (PMID 35053592, 2022). "More recently, we found that Chol-DsiSTAT3 polyplexes suppress endogenous, therapeutically relevant STAT3 mRNA in primary 4T1 breast tumors less than 24 h after the final dose." (PMID 35076584, 2022). "STAT3 is activated by secreted factors within the breast tumor, many of which are elevated and correlate to advanced disease and poor survival outcomes." (PMID 35053592, 2022). "ROS and JAK/Stat3 cooperatively increased HIF-1α expression under normoxia in BM-MSCs in response to factors secreted from breast tumor cells." (PMID 36230633, 2022). "We demonstrated that ROS and JAK/Stat3 synergistically lead to an increase in HIF-1α in BM-MSCs in vitro under normoxic conditions mimicking the breast tumor microenvironment." (PMID 36230633, 2022). "We chose a 48-h timepoint given that Chol-DsiSTAT3 polyplexes maximally suppress STAT3 mRNA in primary murine 4T1 breast tumors 48 h after IV administration." (PMID 35076584, 2022). "Preclinical and clinical studies have shown that constitutive activation of STAT3 can be found in more than 50% of breast tumors, and most of it exists in TNBC." (PMID 34875483, 2022).
breast tumor (continued). "STAT3 is involved in proliferation and suppression of apoptosis of breast tumor cells through the upregulation of target genes cyclin D1, c-myc, Mcl-1, Bcl-2 and Bcl-xL." (PMID 35371975, 2022). "We chose the lowest equimolar dose of Chol-siSTAT3 [2 mg/kg] and Chol-DsiSTAT3 [2.5 mg/kg] that provided maximum suppression of STAT3 mRNA levels in primary 4T1 breast tumors to minimize possible effects of dose saturation in the primary tumor." (PMID 35076584, 2022). "ROS and JAK/Stat3 cooperatively upregulate the expression of HIF-1α in bone marrow-derived mesenchymal stem cells under normoxic conditions in response to breast tumor cells." (PMID 36230633, 2022). "Generally, STAT1 and STAT3 are highly expressed and considered to be among the most important transcription factors in human breast tumors." (PMID 33922837, 2021). "TCGA data analysis revealed the significant aberrant expression of both STAT3 and p300 in breast tumor tissues indicating their crucial role in epigenetic changes during tumorigenesis and metastasis." (PMID 33604794, 2021). "There is considerable evidence that PIN1 regulates the MAPK and STAT3 signaling pathways in breast tumor development through its interaction with MEK1, c-Jun and STAT3." (PMID 33800170, 2021). "Of note, it has been reported that increased 705-tyrosine phosphorylated STAT3 (STAT3-pY705) level was detected in CD8+ T cells of breast tumor tissues." (PMID 33957948, 2021). "Significantly, we show that STAT3 depletion in CD103+ cDC1s leads to increased CD8+ T cell infiltration in murine breast tumors, suggesting this approach overcomes the immunosuppressive breast TME." (PMID 31947933, 2020). "We have previously demonstrated direct tumor-promoting effects of visfatin on breast tumor cells mediated via c-Abl and STAT3, and indirect effects via ADSC intermediaries acting via a GDF15-pAKT pathway." (PMID 33256011, 2020). "In particular, gene profiling of TN breast tumors revealed that STAT3 and NF-κB were highly activated." (PMID 33109232, 2020). "A later study also reported that AKT phosphorylation, integrin expression, and activation of STAT3 signaling pathways were upregulated after CYP27B1 ablation in breast tumors." (PMID 33163485, 2020). "Consistently, our results as well as work from others indicates breast tumors express STAT3-activating cytokines." (PMID 31947933, 2020). "STAT3, while necessary for mammary gland involution, is found in most breast tumors, especially triple negative cancers, and nuclear localization of STAT3 expression appears to be a favorable prognostic marker in patients with invasive breast cancer." (PMID 30497427, 2018). "In breast tumors, persistently-active STAT3 has been found to promote breast tumor progression by facilitating cancer cell proliferation, angiogenesis and EMT6." (PMID 29934528, 2018). "To interrogate the functional significance of STAT1 in limiting the tumorigenic potential of breast tumours with low (MT/Shc2F/2F) versus high (MT/ShcA+/+; MT/Shc313F/313F) STAT3 activity, we deleted STAT1 by CRISPR/Cas9 genomic editing." (PMID 28276425, 2017). "Firstly, signal transducer and activator of transcription 3 (STAT3) is implicated in Twist1 regulation by the observation that Twist1 expression is ablated upon STAT-3 knockdown in breast tumors in immunocompetent mice." (PMID 28099910, 2017). "Impaired Y239/Y240-ShcA phosphorylation selectively reduces STAT3 activation in breast tumours, profoundly sensitizing them to immune checkpoint inhibitors and tumour vaccines." (PMID 28276425, 2017). "A constitutively active STAT3 status is found in about 50–60% of breast tumors specifically in IBC after neoadjuvant chemotherapy, which is associated with tumorigenesis and drug resistance." (PMID 28270211, 2017). "We extended our analysis to include the STAT3 transcription factor, which is essential for breast tumours to evade anti-tumour immunity." (PMID 28276425, 2017).
breast tumor (continued). "MT/ShcA+/+ cells model breast tumours that possess an activated tyrosine kinase/ShcA axis, which simultaneously activates STAT3 and represses STAT1 to establish immune suppression." (PMID 28276425, 2017). "In summary, our data suggests that only breast tumors in which the activation of STAT3 is dependent on IL-6 will be sensitive to therapies against this cytokine." (PMID 27602583, 2016). "Taken together, the results of the present study would suggest an important role for STAT1 and STAT3 in regulating anti-tumour immunity in the breast tumour microenvironment." (PMID 27769057, 2016). "In approximately 50-60% of the primary breast tumors, STAT3 has been reported constitutively activated through phosphorylation by cytoplasmic non-receptor tyrosine kinases." (PMID 26474285, 2015). "Because Stat3 is constitutively activated in ~70% of breast tumors, we determined the level of phospho-Stat3 (Tyr705) in three breast cancer cell lines by western blot analysis." (PMID 25811798, 2015). "We showed that downregulation or inhibition of CXCR7 or STAT3 reduced breast tumor growth and spontaneous metastasis in the orthotopic model by regulating proliferative and angiogeneic pathways." (PMID 24886617, 2014). "STAT3 has been reported constitutively activated in about 50–60% of the primary breast tumors and activated through the phosphorylation of Y705 by cytoplasmic non-receptor tyrosine kinases." (PMID 24297508, 2014). "Accumulating evidences support a role for STAT3 pathway in cancer stem cell functions, particularly in breast tumor-initiating cells." (PMID 25026286, 2014). "In particular, we show that co-expression of HER2 and ER induces phosphorylation of STAT3 in human breast tumors." (PMID 24297508, 2014). "In this study, we showed that STAT3 was phosphorylated in HER2-overexpressing, ER-positive human breast tumors and, furthermore, phosphorylated STAT3 promoted the stem-like cell phenotype." (PMID 24297508, 2014). "Stat3 has multiple functions and appears to play a key role in the development of breast tumor formation." (PMID 24416452, 2014). "STAT3 plays a critical role in the expression of cell proliferative pathways and is known to be activated in breast tumors." (PMID 22824293, 2012). "Rac1+ epithelial cells in breast tumours also contain high levels of the phosphorylated form of the transcription factor STAT3." (PMID 22689141, 2012). "ZIP6 over-expression in breast tumors and cancer cell lines is correlated with phosphorylated (activated) STAT3 and Snail expression in breast tumor biopsies is positively associated poor survival." (PMID 23016122, 2012). "We examined Rac1 and phospho-Ser727 STAT3 levels by antibody staining in human breast tumours (n=6)." (PMID 22689141, 2012). "Breast tumors expressing high levels of activated Stat3 are inversely correlated with a complete pathological response to neo-adjuvant chemotherapy." (PMID 22140473, 2011). "In order to identify additional Stat3 targets responsible for metastatic spread, we used gene expression profiling of primary breast tumors." (PMID 22140473, 2011). "In summary we have determined that activated Stat3 expression is heterogeneous in distribution in primary breast tumors with the highest levels found on the tumor edge." (PMID 22140473, 2011). "In vivo killing competence of MSCs carrying Adv-Stat3(-) toward breast tumor was analyzed by comparison of tumor volumes and survival periods." (PMID 22054049, 2011). "We determined that signal transducer and activator of transcription 3 (Stat3) is tyrosine phosphorylated in 37% of primary breast tumors and 63% of paired metastatic axillary lymph nodes." (PMID 22140473, 2011). "Stat3 is constitutively activated in more than 50% of primary breast tumors and tumor-derived cell lines." (PMID 17531096, 2007).
breast tumor (continued). "Janus kinase inhibitors and monoclonal anti-IL6 receptor antibodies significantly decrease ALDH expression, colony, and mammosphere formation, suggesting possible use of pharmacological inhibitors of the IL-6/JAK2/STAT3 pathway in breast tumors with elevated POU1F1 levels." (PMID 41857068, 2026). "Blocking the leptin-STAT3-FAO pathway reactivates breast tumor CD8+ T cells." (PMID 40612678, 2025). "In addition to the GPER and EFGR pathways, BPA can also act by activating vascular endothelial growth factor (VEGF), leading to angiogenesis in breast tumors, activating STAT3 signaling, and activating the MAPK signaling pathway." (PMID 41440754, 2025). "STAT3 activity was evident in the macrophages infiltrating the FN-EDA-rich areas of breast tumors." (PMID 36922898, 2023). "For example, aberrant STAT3 signaling promotes breast tumor progression through deregulation of the expression of downstream target genes, which control proliferation (Bcl-2, Bcl-xL, survivin, cyclin D1, c-Myc, and Mcl-1), angiogenesis (Hif1α and VEGF), and EMT (vimentin, Twist, MMP-9, and MMP-7)." (PMID 36446524, 2023). "Thus, Chol-siRNA polyplexes and Chol-DsiRNA polyplexes have similar potencies and efficacies against STAT3 mRNA in primary murine syngeneic breast tumors after IV administration at the current N/P ratios." (PMID 35076584, 2022). "A key finding of the present study is that both Chol-siSTAT3 polyplexes and Chol-DsiSTAT3 polyplexes maintain the suppression of STAT3 mRNA in primary 4T1 breast tumors less than 24 h after IV administration of a single equimolar dose [0.50 mg Chol-DsiSTAT3/kg or 0.41 mg Chol-siSTAT3/kg]." (PMID 35076584, 2022). "IL-6-induced signaling in breast tumors mainly triggers STAT3 activation." (PMID 35163731, 2022). "STAT3 is critical for the growth of murine 4T1 breast tumors." (PMID 35076584, 2022). "Thus, Chol-siSTAT3 polyplexes and Chol-DsiSTAT3 polyplexes suppress STAT3 mRNA in primary murine syngeneic breast tumors with similar kinetics after IV administration below tumor-saturating doses at the current N/P ratios." (PMID 35076584, 2022). "A positive correlation between phosphorylated STAT3 (pSTAT3) and IL-6 expression in primary breast tumors was first reported by Berishaj and collaborators, who also demonstrated that in vitro blockade of gp130 or IL-6 sequestration led to a decrease of pSTAT3 levels." (PMID 35163731, 2022). "Moreover, inhibition of CD8+ TEFF cells via STAT3 decreased breast tumor burdens and lung metastasis incidence in the Mouse Mammary Tumor Virus-Polyoma Virus Middle T antigen (MMTV-PyMT) transgenic mice." (PMID 33957948, 2021). "The YHD inhibition of 4T1 breast tumor growth may be related to the negative regulation of the JAK/STAT3 pathway by repressing the expression of IL-6 and TGF-β (Mao, Feng & Gong, 2018)." (PMID 32461838, 2020). "The derivation of a STAT3 pathway signature that predicts poor prognosis and resistance to endocrine therapy indicates that a subpopulation of ER+ breast tumors might be the rational targets for SFX-01 therapy in combination with current endocrine therapies." (PMID 32472077, 2020). "We further investigated whether STAT3 and pSTAT3+ myeloid cells exist in circulation and in the BC microenvironment of breast tumors." (PMID 33679700, 2020). "Furthermore, ILEI is an oncogenic cytokine that can bind to LIFR and trigger EMT and CSC traits of breast tumors via STAT3 activation." (PMID 32651426, 2020). "Here, we identify the SP1 transcription factor as an essential mediator of RhoU transcriptional activation downstream of the WNT/PCP pathway, and we unveil a functional cooperation between WNT/PCP/JNK1, RHOU, SP1 and STAT3 to promote cell motility in basal-like human breast tumor cells." (PMID 30654518, 2019).